CCL4 (C-C motif chemokine ligand 4)
Diseases named in the same sentence as CCL4 in open-access papers (continued):
Sharing a sentence is not in itself a finding about the gene and the disease.
COVID-19 (continued). "Mon HLA and Mon CD14 inside Delta samples differ in expression for the cytokine panel (CCL3, VEGFA, CCL5, CCL4, CXCR4, IL7R, CXCL8, and PF4) that have been found associated with COVID-19 severity and mortality." (PMID 36230912, 2022). "We reported that patients affected by COVID-19 showed an increase of plasma level of cytokines with different properties, such as CCL4, IL-10, and PD-L139." (PMID 34326336, 2021). "Two cytokine-associated genes (CCL4 and CD40) were dysregulated in COVID-19 and single VTE, and one cytokine-associated gene (CCL4) was dysregulated in COVID-19 and recurrent VTE." (PMID 34071557, 2021). "Cytokine CCL4 has been shown to be upregulated in COVID-19 patients and in patients who develop cardiovascular diseases." (PMID 34071557, 2021). "Their results revealed host inflammatory cytokine profiles to SARS-CoV-2 infection in patients and highlighted the association between COVID-19 pathogenesis and excessive cytokine releases such as CCL2/MCP-1, CXCL10/IP-10, CCL3/MIP-1A, and CCL4/MIP1B." (PMID 34441862, 2021). "Higher expression of CXCL9 in COVID-19 patients than healthy controls and higher levels of CCL4 in severe COVID-19 patients were also found." (PMID 34760386, 2021). "These cytokines, such as IL-6, IL-7, CCL-2/MCP-1, CCL-3/CCL-4 MIP-1α/β, TNF-α, and G-CSF, have been implicated in COVID-19 pathogenesis." (PMID 34341347, 2021). "Our results reveal distinct host inflammatory cytokine profiles to SARS-CoV-2 infection in patients, and highlight the association between COVID-19 pathogenesis and excessive cytokine release such as CCL2/MCP-1, CXCL10/IP-10, CCL3/MIP-1A, and CCL4/MIP1B." (PMID 32228226, 2020). "Transcriptome analysis of BALF samples indicated that the levels of pro-inflammatory chemokines such as CXCL1, CXCL2, CXCL6, CXCL8 (IL-8), CXCL10 (IP-10), CCL2 (MCP-1), CCL3 (MIP-1A), and CCL4 (MIP-1B) are elevated in patients with COVID-19, which correlated with disease severity." (PMID 36111104, 2022). "Six hub genes (FCGR3A, CD69, IFNG, CCR7, CCL5, and CCL4) were involved in regulating immune cells in COVID-19 and HF, which may contribute to the pathogenesis of HF." (PMID 36420258, 2022). "Indeed inflammatory chemokines CCL2, CCL3 and CCL4 have been found at higher concentrations in the airways compared to the plasma in patients with severe COVID-19." (PMID 34614036, 2021). "The upregulation of CCL4 was much greater in COVID-19 than in VTE, however." (PMID 34071557, 2021). "A crucial element of immune response to infection (CCL4) was related to COVID-19, whether it is a target of intervention to prevent COVID-19 warrants further investigation." (PMID 34163532, 2021). "CCL4 recruits immune cells, including macrophages, monocytes, and T cells, suggesting that COVID-19 and VTE may both exhibit the increased recruitment of inflammatory immune cells." (PMID 34071557, 2021). "Chemokines such as CCL4L2, CCL3, and CCL4 and their respective receptors were also found to be enriched in severe-stage monocytes, indicating the potential of targeting these cytokines and/or their receptors with drugs for treating severe-stage COVID-19 patients." (PMID 32764665, 2020). "Multiple studies show high levels of proinflammatory cytokines such as IL-1, TNF, IFNs, IL-6, IL-8, IL-18, IL-17α, G-CSF, and GM-CSF, as well as chemokines, such as MCP-1, IP-10, MIP-1α, CXCL10, CCL2, CCL4, CCL14, CCL19, and CCL25 in severe cases of COVID-19." (PMID 40076291, 2025). "The analysis of cord blood samples at Early and Intermediate convalescent COVID-19 showed increased levels of CCL11, CCL3, CCL4, CCL2, IL-1β, IFN-γ, IL1-Ra, G-CSF, and IL-7 and a decrease of IL-10 and IL-2 as compared with HC." (PMID 40821818, 2025). "Meanwhile, five proteins exert protective effects against hospitalization and progression to critical COVID-19 (OR: 0.85~0.95), including CXCL11, CDCP1, CCL4/MIP, IFNG, and LIFR." (PMID 38455043, 2024).
COVID-19 (continued). "For instance, analysis of transcriptomic data in bronchoalveolar lavage of a patient with COVID-19 found high expression of CCL2, CCL3, CCL4, and CXCL10 when compared to healthy donors." (PMID 37632046, 2023). "In symptomatic or asymptomatic COVID-19, the CCL3, CCL4, and CCL5 chemokines were detected in a similar fashion." (PMID 36016187, 2022). "We observed increased levels of chemokines MCP-1 (CCL2), IP-10 (CXCL10), MIP1β (CCL4) and IL-8 (CXCL8) in COVID-19 patients." (PMID 35529862, 2022). "According to a recent study, the levels of CCL4 and CCL5 were increased in all three groups of patients suffering from COVID-19, namely, mild, severe, or fatal, but these chemokines were significantly higher only in mild cases." (PMID 36016187, 2022). "In post-COVID-19 patients, some plasma cytokines (i.e. TNF-α, IL-18, CXCL8, CXCL10, CCL2, CCL3, and CCL4) remained higher than in HCs, but levels were much lower as compared to hospitalised patients." (PMID 36275702, 2022). "An increased expression of CCL3, CCL4, CSF2, IL1B, and LTA was found in the revaccinated groups (groups 5 and 6), which in fact experienced decreased expression in severe COVID-19 patients." (PMID 36225326, 2022). "After stimulating myeloid blood cells with R848, we observed that multiple myeloid subsets from COVID-19 patients had lower levels of IFNβ and higher levels of TNF, IL-6, IL-12, CCL3, and CCL4 than cells from healthy controls." (PMID 36085197, 2022). "CD4 T-cells with cytotoxic activity (CD4 CTLs) and NK-cells displayed enhanced interferon signaling and effector activation markers (GZMB, GZMH, CCL4, XCL2) in patients who succumbed to COVID-19." (PMID 35169146, 2022). "Plasma levels of IL-1RA, IL-10, IL-15, and G-CSF and of the chemokines CCL3, CCL4, CXCL8, and CXCL10 were significantly increased in patients with COVID-19 compared with those of healthy controls." (PMID 34793331, 2022). "Alongside, we observed a high expression of cytokines (CCL3, CCL4, CCL5, CCL7, CCL18 and CCL20) in the CD4+ TCM, Classical monocytes and NK cells in the COVID-19 patients." (PMID 36532041, 2022). "In contrast, CD4 CTL T-cells and NK-cell subsets displayed increased expression of effector activation markers (GZMB, GZMH, CCL4, XCL2) and ISGs in patients who succumbed to COVID-19." (PMID 35169146, 2022). "This also showed that stimulation post-BCG vaccination increased expressions of BIRC3, CCL3, CCL3L1, CCL4, CSF2, IL1B, and LTA, which in contrast, decreased in severe COVID-19." (PMID 36225326, 2022). "Of the 16 mediators elevated in early COVID-19 compared with healthy controls, 11 decreased over time (CCL3, CCL4, TNF-α, IL-6, CCL13, IL-4, IFN-α2a, CXCL10, CXCL11, IL-2, and IL-12)." (PMID 35397798, 2022). "In severe COVID-19 lung macrophages displayed high expression of IL-1β, IL-6, TNF-α and various chemokines (CCL2, CCL3, CCL4, CCL7, CXCL9, CXCL10 and CXCL11)." (PMID 34054832, 2021). "Levels of IL-6, IL-10, IL-15, IFN-γ, TNF-α, CCL2, CCL3, CCL4, CCL26, CXCL9 and CXCL10 were significantly elevated both in COVID-19 critical clinical condition and in MAS patients as compared to healthy controls." (PMID 34226537, 2021). "After comparing the collected genes, 460 host factors common to COVID-19 and dengue were found, including MMP2, PDF, PFKP, SLC25A3, IGF1, CCL4, TLR4, and AhR, and further analysis of interaction networks was performed." (PMID 34394108, 2021). "Cytokine-related genes that were found to be dysregulated in both CAD patients and COVID-19 patients include chemokines (CCL3 and CCL4), chemokine receptor CXCR1, and a TNFSF gene, LTB." (PMID 34071557, 2021). "The increase in blood concentrations of different cytokines such as interleukins and chemokines such as IL-6, IL-8, IL-10, TNF-α, IL-1β, IL-2, IP-10, MCP-1, CCL3, CCL4, and CCL5 has been described for COVID-19 patients." (PMID 34262570, 2021).
COVID-19 (continued). "This was observed for TGFB3, CCL4, IL15, and IL20RA in both ICM samples vs. COVID-19 samples and NIDCM samples vs. COVID-19 samples." (PMID 34071557, 2021). "Its chemokine ligands CCL-5 (RANTES), CCL-3, CCL-4 (also known as MIP-1α and 1β, respectively), and CCL-3L1 are upregulated in severe COVID-19 cases." (PMID 33445810, 2021). "S2, C and D) were also identified as DEGs in BAL NK cells of COVID-19 patients as compared with controls, including GZMB (granzyme B), PRF1 (perforin), HAVCR2 (Tim-3), and CCL4 (MIP-1β)." (PMID 32826343, 2020). "Our results showed upregulation of chemotactic factors, including CCL4, CCL8, and CCL11, that all shared CCR5 as their receptor, as a common derangement observed in both diseases; RA and COVID-19." (PMID 32923679, 2020). "In COVID-19, men demonstrated lower expression of cytokines with protective effects against viral infection, including CCL2, CCL3, CCL4 and CXCL16, than women." (PMID 32974111, 2020). "Similar to EVALI, patients with COVID-19 showed elevated levels of several cytokines (CCL2/MCP-1, CXCL10/IP-10, CCL3/MIP-1A, and CCL4/MIP1B) in BALF and peripheral blood mononuclear cells." (PMID 32528233, 2020). "Supervised machine learning algorithm (RF) was used to predict the COVID-19 severity and chronicity based on immune subset profiling and a 14-plex cytokine panel (TNF-a, IL-4, IL-13, IL-2, GM-CSF, sCD40L, CCL5, CCL3, IL-6, IL-10, IFN-g, VEGF, IL-8, and CCL4." (PMID 40657638, 2025). "Venn diagram analysis identified a set of common soluble immune mediators with fold change magnitude over 1.5× up to 15.7× in cord blood samples according to mother serum in all COVID-19 subgroups, comprising CCL11, CCL4, IFN-γ, PDFG, and G-CSF (* below bar charts)." (PMID 40821818, 2025). "Six chemokines (CXCL9, CXCL10, CCL4, CCL5, CCL27, and CXCL12) and eight interleukins (IL-1Ra, IL-2Ra, IL-3, IL-5, IL-9, IL-12p40, IL-15, and IL-16) were increased in both PLWH/COVID-19 and COVID-19-only." (PMID 41516165, 2025). "CCL4 was only detectable in the Covid groups; therefore, it was analyzed only in the context of COVID-19 and not in TTP." (PMID 39337495, 2024). "BAL alveolar macrophages from severe COVID-19 patients (n = 23) were characterized by an increased production and release of several pro-inflammatory mediators, such as IL-1β, IL-6, CCL3 and CCL4 and increased expression of IL-1R and S100A8/9 proteins, compared to those from mild COVID-19 patients." (PMID 36941580, 2023). "While some genes involved in monocyte and lymphocyte migration and function were expressed in the COVID-19(+) TV group (CCL13, CCL8, and CCL20), a greater number of these genes were expressed in the COVID-19(-) PU control group (CCL19, CCL18, CXCL13, CCL4, CCL5, CXCL9)." (PMID 37026002, 2023). "We also did not detect an increase in CCL3 and CCL4 antibodies in COVID-19 convalescents compared with healthy controls in the Lugano cohort at month 6, although the amount of corresponding chemokines was elevated in their plasma." (PMID 36879067, 2023). "Moreover, the levels of IL-8, CCL2, CCL3, CCL4, CCL7, CCL12, and CX3CL1 were higher in both the serum and CSF samples of COVID-19 cases with neurological syndrome (NS)." (PMID 35464491, 2022). "Controversially, another study indicated that in severe COVID-19 cases, peripheral blood monocytes significantly increased expression of IL-6, TNF, IL-1β, and their receptors, as well as pro-inflammatory chemokines including CCL2, CCL3, and CCL4." (PMID 35632823, 2022). "Compared to healthy controls, CD16+ monocytes from people with COVID-19 had significantly upregulated expression of genes involved in inflammation including cytokines and chemokines, such as IL-1β, CXCL8, CCL3 (MIP-1α), and CCL4 (MIP-1β)." (PMID 34108966, 2021). "Interestingly, COVID-19 individuals (including PASC, Mild, Severe) show high levels of CCL5, a chemokine that like CCL4 signals through CCR5." (PMID 34262570, 2021).
COVID-19 (continued). "In brief, the scRNA-seq followed by the immune transcriptomic analysis indicated an activation state (through CD69 and HLA class II genes), chemotaxis (e.g., CCL3 and CCL4), an inflammatory state (e.g., NFKBIA, PIK3R1, S100A9, etc.)in T cells, especially in CD8+T cells, in COVID-19 cases." (PMID 33717140, 2021). "Cytokine-related genes that are dysregulated in both cardiomyopathy patients and COVID-19 patients include chemokines (CCL3, CCL4, CXCL4, etc.), interleukins or interleukin receptors (IL15, IL20RA, etc.), and genes in the transforming growth factor beta (TGFB) family." (PMID 34071557, 2021). "While CXCL9, CXCL10 and CXCL11 expression levels were increased both in moderate and severe disease compared to healthy levels, IL1β, IL6, TNF as well as CCL2, CCL3, CCL4 and CCL7 were expressed at higher levels in lung macrophages from patients with severe COVID-19." (PMID 34367190, 2021). "Regarding the downregulated geneset, MHC II molecules, including HLA-DQA1, HLD-DRA, HLA-DRB1, HLA-DMB, HLA-DMA, etc., and cytokine/chemokine genes, including IL1B, TNF, CCL3, CCL4, and CXCL8 were expressed at lower levels in COVID-19 patients, especially those with severe diseases." (PMID 33101705, 2020). "The mediators CCL3, CCL4, CCL2, CCL5, IL-12, IL-15, IL-1Ra, and PDGF were higher in healthy volunteers, while the mediators CCL11, CXCL10, IL-1b, IL-6, TNF-a, IFN-g, IL-17, IL-9, IL-10, IL-13, FGF-basic, G-CSF, GM-CSF, IL-7, and IL-2 were increased in COVID-19 positive patients." (PMID 37903875, 2023). "To explore whether the leucocyte response is limited by COVID-19, we stimulated cells with LPS or PMA/Ion, and a clear proinflammatory response with cytokines such as TNF-α, CCL3, CCL4, IL-17a, CCL23 and CXCL8 was detected in the supernatant, indicating that leucocytes are not anergic." (PMID 35901034, 2022). "Such chemokines are able to recruit polymorphonuclear cells, such as monocytes, memory T cells, NK cells, and neutrophils in the site of infection and pregnant COVID-19 women were characterized by higher levels of CCL4, CCL5, and CXCL2 if compared with pregnant women without infection." (PMID 34326336, 2021). "Consistently, in this study we found the expression of a large number of cytokines are significantly elevated in COVID-19 patients BALF samples compared to control, including pro-inflammatory cytokines CXCL1, CXCL2, CXCL6, CXCL8, CXCL10/IP-10, CCL2/MCP-1, CCL3/MIP-1A and CCL4/MIP1B." (PMID 32228226, 2020). "However, CCL-4 levels among COVID-19 recovered individuals have not been described." (PMID 38646483, 2024). "Between COVID-19 patients and healthy controls, median chemokine concentrations (CCL2 and CCL4) were not statistically significant (P > 0.05)." (PMID 35958594, 2022). "In our study, we first showed that despite similar respiratory severity, plasma concentrations of numerous cytokines characterizing the “cytokine storm” (i.e. IL-1β, IL-6, IL-8, IL-15, TNF-α, CCL2, CCL4, CCL19, CCL20, TGF-α) were lower in COVID-19 compared to non-COVID-19 patients." (PMID 33272291, 2020).
melanoma (87 papers, 2010 to 2026). A malignant, usually aggressive tumor composed of atypical, neoplastic melanocytes. "A database analysis and immunohistochemistry showed that CCL4 was associated with better overall survival in primary melanoma patients." (PMID 38928238, 2024). "Wnt/b-catenin was associated with reduced CCL4 expression, which inhibited subsequent DC and T-cell recruitment in melanoma." (PMID 35664743, 2022). "In melanomas with activating mutations in the Wnt/β-catenin signaling pathway, C-C chemokine ligand 4 (CCL4) is downregulated, which reduces the migration of CD103+ DCs and leads to a deficiency in CD8+ TILs." (PMID 34359568, 2021). "Furthermore, tumor-derived CCL4 has also been linked with the recruitment of DC cells in a mouse model of melanoma." (PMID 30873179, 2019). "Functionally perturbing oncostatin M-oncostatin M receptor signalling, a proposed MIDAS target, in TRACERx melanoma-patient-derived explants yielded reduced dysfunctional CD8+ T cells, which associate with immunotherapy response, and reduced CCL4 levels." (PMID 42206145, 2026). "We noted that the lung cancer tumor bed contained a higher relative concentration of CCL3 and CCL4 compared with that of melanoma." (PMID 40553564, 2025). "In a B16 melanoma model, the upregulation of CCL4 and CCL5 recruited Tregs in a CCR5-dependent manner and promoted tumor progression." (PMID 38928238, 2024). "Melanoma cell-intrinsic activation of β-catenin inhibits CCL4 expression and suppresses recruitment of dendritic cells and T cells, conferring immunotherapy resistance." (PMID 38997291, 2024). "Exhausted T cells within melanoma tumors also produce CCL4 and CXCL13, which in turn recruit other relevant immune cells from the circulation such as dendritic or B cells, potentially resulting in tertiary lymphoid structures." (PMID 38562921, 2024). "A higher expression of CCL2, CCL3, CCL4, CXCL9 and CXCL10 transcripts was associated with more CD8+ T cell recruitment into melanoma metastases." (PMID 38928238, 2024). "In melanoma, the transcription repressor ATF3 induced by the Wnt/ß-catenin pathway has been associated with CCL4 repression." (PMID 39008536, 2024). "This includes CD8+ T cells but also basophils, which were able to produce CCL4 and contribute to tumor rejection in a mouse melanoma model." (PMID 38928238, 2024). "In Wnt/β-catenin-positive melanoma tumors, decreased production of chemokine CCL4 leads to reduced recruitment of BATF3 DCs to the TME." (PMID 34983532, 2022). "Active β-catenin signaling in melanoma cells promotes T-cell exclusion through decreased chemokine ligand 4 (CCL4) production by tumor cells." (PMID 36231010, 2022). "Up-regulation of β-catenin signaling leads to a reduction of CCL4 secretion from tumor and this prevents DC recruitment into the murine melanoma TME." (PMID 36275666, 2022). "Activated transcription factor 3 (ATF3) expression is induced by β-catenin in melanoma cells, which suppresses C-C motif chemokine ligand 4 (CCL4) gene transcription." (PMID 36232859, 2022). "This negative feedback was substantiated by then demonstrating that gene knockdown of ATF3 and CTNNB1 in melanoma cell lines led to upregulation of CCL4 expression." (PMID 33672668, 2021). "In general, increased tumor immune infiltration significantly improves survival in melanoma patients, therefore CCL4 was the potential predictive biomarker most likely to respond to immunotherapy of melanoma." (PMID 34805163, 2021). "In melanoma, aberrantly active β-catenin signaling in melanoma cells suppresses CCL4 expression to abolish cDC1 infiltration." (PMID 34290401, 2021). "Activation of Wnt/β-catenin signaling in melanoma was identified to inhibit T cell infiltration, leading to tumor growth and immunotherapy resistance via reducing CCL4 secretion." (PMID 34462446, 2021).